Y_RNA (Y RNA )
Gene: Miscellaneous RNA gene on chromosome X (71,491,066 to 71,491,167, reverse strand). Ensembl gene ENSG00000199751.
Homologues: Orthologues: chimpanzee Y_RNA (100% identical). Paralogues in human: Y_RNA (92% identical), RNY3 (91% identical), RNY3P1 (91% identical), Y_RNA (91% identical), Y_RNA (90% identical), Y_RNA (89% identical), RNY3P14 (88% identical), Y_RNA (88% identical), RNY3P16 (87% identical), Y_RNA (87% identical), Y_RNA (86% identical), RNY3P11 (85% identical), and 97 more.